GATA3 (GATA binding protein 3)
Diseases named in the same sentence as GATA3 in open-access papers (continued):
Sharing a sentence is not in itself a finding about the gene and the disease.
allergic asthma (32 papers, 2011 to 2026). A asthma with a basis in a pathological type I hypersensitivity reaction. "In models of allergic asthma, the overexpression of Gata-3 has been shown to increase susceptibility to allergic airway inflammation." (PMID 40870825, 2025). "More recently in the context of allergic asthma, NF-κB signaling has been implicated in GATA3 induction and subsequent TH2 polarization." (PMID 39803487, 2024). "ILC2 cells, which express the Th2 transcription factor GATA3, have been associated with allergic asthma." (PMID 35281014, 2022). "The anti-inflammatory activities of curcuminoids in several studies have shown that curcumin was able to regulate receptor levels of Notch1/2 and GATA3 in acute allergic asthma caused by inflammation in BALB/c mice." (PMID 33322573, 2020). "It is well known that overexpression of GATA-3 predisposes for Th2-mediated diseases such as allergic asthma and suppression of GATA-3 expression in the lung reduces IL-4, IL-5, and IL-13 productions concurrently." (PMID 23800145, 2013). "It is well known that overexpression of GATA-3 predisposes for Th2-mediated diseases such as allergic asthma whereas activation of T-bet appears to be an essential step for Th1-mediated mucosal diseases such as Crohns, disease." (PMID 21772663, 2011). "Moreover, Th2-like Treg cells expressing GATA3 are strongly associated with the pathogenic progression of allergic asthma." (PMID 39199350, 2024). "Together, these findings identify HuR as a therapeutically targetable upstream regulator of GATA3-driven type 2 inflammation in allergic asthma." (PMID 42094570, 2026). "OVA-induced airway inflammation and Th2-mediated allergic asthma were suppressed by oral oleanolic acid, including by inhibiting the transcription factors GATA-3 and RORγt and promoting the transcription factors T-bet and Foxp3." (PMID 39796399, 2025). "GATA3 has previously been shown to have strong links to allergic asthma and the promotion of Th2 differentiation and the resulting release of cytokines regulating ASM contractility, including IL-13 and IL-5." (PMID 40131902, 2025). "Cyanidin-3-O-glucoside (C3G) prevented the progression of allergic asthma in a murine model through STAT6/GATA3 signaling suppression, whereas another cyanidin, procyanidin A2, reduced the expression of CCL26 in human keratinocytes via JAK1/STAT6 signaling." (PMID 35566102, 2022). "Krug and coworkers found that cleaved and inactive GATA-3 mRNA can attenuate the asthmatic response and Th2-regulated inflammatory response in patients with allergic asthma." (PMID 34126986, 2021). "The GATA3 specific DNAzyme (SB010) is an oligonucleotide which can mediate the cleavage of the mRNA of the transcription factor GATA3 and its possible therapeutic usage in human diseases was first investigated in patients affected by allergic asthma." (PMID 31068803, 2019). "Here we report that mice lacking Bcl11b in mature T-cells have a diminished capacity to mount Th2 responses during helminth infection and allergic asthma, showing reduced Th2 cytokines and Gata3, and elevated Runx3." (PMID 29700302, 2018). "Taken together, these results indicate that picroside II has protective effects on allergic asthma by reducing GATA3 expression and Th2 cytokine bias." (PMID 27870920, 2016). "We investigated whether the RNA-binding protein HuR (ELAVL1) functions as a post-transcriptional regulator of GATA3-driven type 2 inflammation in allergic asthma." (PMID 42094570, 2026). "Further studies showed that SOX12 promoted GATA3 ubiquitination mediated by E3 ubiquitin ligase F-Box and WD repeat domain containing (Fbw) 7 and induced GATA3 degradation through proteasome pathway, thus inhibiting Th2 cell differentiation and development of allergic asthma." (PMID 40893770, 2025). "Interestingly, GATA3 RNA modulating therapies have been reported to target Th2-cell response in allergic asthma delivered via nasal inhalation." (PMID 34337671, 2021).
allergic asthma (continued). "Then we considered whether Notch–GATA3 signaling pathway was an important pathway in allergic asthma and whether it could be inhibited by curcumin." (PMID 24706026, 2014). "Butyrate is considered an anti-allergic asthma treatment, which suppresses pro-inflammatory cytokines secretion and GATA binding protein 3 (GATA3) expression in the human pulmonary Group 2 Innate lymphoid cells (ILC2s)." (PMID 33339172, 2020). "In the pathogenesis of allergic asthma (without hyperoxia), allergens, pollutants, and infectious agents induce GATA-3 transcription factor activation and chemokine CCL2 (MCP-1) expression which promote T cell differentiation toward TH2 and activation of macrophages M2." (PMID 26417446, 2015).
gastric cancer (31 papers, 2012 to 2025). A primary or metastatic malignant neoplasm involving the stomach. "GATA-3 has been demonstrated to be involved in the progression of H. pylori-associated gastric cancer in our previous findings, which was explained by the decreased Cx32 and Cx43 expression and disordered gap junction in vitro and in vivo." (PMID 29138530, 2017). "GATA-3, a critical regulator for type 2 immunities including ILC2s and Th2 cells, has been firstly found upregulated in H. pylori-associated gastric cancer from our previous differential screening of transcription factor expression." (PMID 29138530, 2017). "Cox hazard ratio regression analyses further demonstrated that the GATA3 expression level is an independent risk factor for overall survival, suggesting that this value may serve as a prognostic biomarker for gastric cancer patients after surgery." (PMID 24504018, 2014). "The positivity rate of GATA-3 in gastric cancer patients is only 5%, making it an important basis for distinguishing between primary and secondary malignant tumors." (PMID 40919150, 2025). "USP21 deubiquitinates MAPK1 by interacting with GATA3, impacting gastric cancer growth and stem cell properties." (PMID 39605891, 2024). "Weak T-bet expression and/or strong GATA3 expression accounts for predominant Th2 type cytokines in gastric cancer patients." (PMID 33144870, 2020). "GATA-3, known as a critical transcript factor for both ILC2s and Th2 cells, was found to be increased in H. pylori-infected gastric cancer tissues." (PMID 29138530, 2017). "Our results suggested that GATA3 plays vital roles in different developmental stages of gastric cancer." (PMID 27403158, 2016). "Further functional experiments are necessary to better understand the function of GATA3 in gastric cancer." (PMID 27403158, 2016). "Kaplan-Meier survival analysis showed a significant correlation between low GATA3 expression and poor clinical outcome in gastric cancer patients after operation." (PMID 24504018, 2014). "Our results showed significantly decreased expression of GATA3 in gastric cancer tissues and confirmed the expression of GATA3 as an independent risk factor for primary gastric adenocarcinoma patients." (PMID 24504018, 2014). "In conclusion, the present study suggests that GATA3 expression is correlated with the clinicopathological parameters of gastric cancer patients and that its low expression independently predicts worse overall survival in patients with gastric adenocarcinoma." (PMID 24504018, 2014). "The mRNA expression levels of RORα and GATA3 were significantly increased in patients with gastric cancer compared with healthy controls." (PMID 24741632, 2014). "Future studies in this field are necessary, as a better understanding of the function of GATA3 in malignancies has the potential to improve the prognosis of gastric cancer." (PMID 24504018, 2014). "Relationship between the GATA3 expression and clinicopathologic features of patients with gastric cancer (n = 402)." (PMID 24504018, 2014). "In this experiment, we supposed that the predominant expression of Th2 type cytokines was related to lower expression of T-bet or higher expression of GATA3 in PBMC from patients with gastric cancer." (PMID 23243425, 2012). "We examined the correlation between the mRNA levels of Hlx and T-bet or GATA3 in PBMCs of gastric cancer patients (90 cases)." (PMID 23243425, 2012).
gastric cancer (continued). "KIAA1429 has been shown to affect a variety of cancers through different pathways, including promoting the progression of hepatocellular cancer through the posttranscriptional modification of m6A relying on GATA3 and regulating cell proliferation in gastric cancer by directly targeting c-jun mRNA." (PMID 36389678, 2022). "Our data indicated that acupuncture and moxibustion promotes a typical Th1 cells drifting by upregulating T-bet/IFN-γ and downregulating GATA3/IL-4, enhancing immune inhibition of advanced gastric cancer which originally exhibits predominant expression of Th2 type cytokines." (PMID 33144870, 2020). "Secondly, GATA-3 was firstly found to be increased in the interstitial lymphocytes from H. pylori-associated gastric cancer, among them, Lin−GATA-3+ cells and Lin+GATA-3+ cells were also found to be enhanced, which indicated an important role for ILC2s in H. pylori infection." (PMID 29138530, 2017). "The expression level of GATA3 was significantly increased in patients with gastric cancer." (PMID 27403158, 2016). "In our study, GATA3 was upregulated in gastric cancer compared with the normal tissues, which may be partly related to the TNM stage of patients with gastric cancer." (PMID 27403158, 2016). "Additionally, we identified the relationship between GATA3 expression and clinicopathological features, and we evaluated the prognostic value of the GATA3 expression level to post-resection survival in gastric cancer." (PMID 24504018, 2014). "However, the functional role and mechanisms of GATA3 in gastric cancer are unclear and require further investigation." (PMID 24504018, 2014). "However, the molecular mechanisms involved in the regulation of GATA3 in gastric cancer require further investigation." (PMID 24504018, 2014). "This analysis lead to the observation that, in the context of H. pylori infection, CVID-associated gastric cancer harboured more abundant GATA3+ and CD8+ T cells in comparison with non-CVID gastric cancer, as observed in non-neoplastic mucosa in the whole series." (PMID 32575504, 2020). "Likewise, our observations are consistent with the idea that GATA3 acts as a tumor suppressor and suggest that it might play an important role in tumor progression in gastric cancer." (PMID 24504018, 2014). "In gastric cancer, USP21 increased the expression level of MAPK1 to promote malignant progression by binding and stabilizing the transcription factor GATA3." (PMID 38906857, 2024). "GATA3 is a substrate of USP21 involved in immune tolerance, and this interaction was also found in gastric cancer, which further facilitated the malignant progression of gastric cancer by promoting MAPK1 (also known as ERK2) expression." (PMID 35846989, 2022). "In this study, we found that the putative STAT3 target, SPG20, is epigenetically silenced in gastric cancer, similar to our previous findings of two other STAT3-epigenetically silenced targets, NR4A3 and GATA3." (PMID 31194837, 2019). "Subsequently, IHC and western blot were performed on adjacent normal and tumor tissues extracted from gastric cancer patients to find that Th2 cell markers such as STAT6, GATA3 and the M2 cell polarization marker CD163 were significantly increased in patients with high ITGA5 expression levels." (PMID 33711961, 2021). "We observed an increase of CD8+/GATA3+ lymphocytes of gastric cancers compared to non-neoplastic mucosa in non-CVID patients along with a lack of significant difference in immune cell counts in CVID-patients." (PMID 32575504, 2020). "Specifically, we observed that, in non-neoplastic mucosa adjacent to gastric cancer, GATA3+ T cell counts were similar in CVID and non-CVID patients with H. pylori infection." (PMID 32575504, 2020). "The levels of GATA3 mRNA in 38 pairs of resected specimens (tumor tissue samples and matched adjacent non-tumor tissue samples) from eligible gastric cancer patients were estimated by RT-qPCR." (PMID 24504018, 2014).
gastric cancer (continued). "Notably, in non-neoplastic mucosa adjacent to gastric cancer, GATA3+ T cell counts in the lamina propria were similar between CVID (n = 8) and non-CVID (n = 6) patients with a history of H. pylori infection (p = 0.065)." (PMID 32575504, 2020). "GATA3 was demonstrated to interact with HIF-1α to enhance cancer cell invasiveness, and inhibition of HHIP promoter methylation suppressed human gastric cancer cell proliferation and migration, which would affect the treatment and prognosis of patients with gastric cancer." (PMID 31281358, 2019). "Accordingly, we have detected GATA-3 in gastric cancer tissues and found that GATA-3 was strongly upregulated in the mesenchyme of H. pylori+ gastric cancer tissues, while the GATA-3-positive cells were nearly much less in the H. pylori− gastric cancer tissues or paired normal gastric tissues." (PMID 29138530, 2017). "Our data showed that the mRNA expression levels of the transcription factors RORα and GATA3, the receptors T1/ST2 and IL-17RB, surface markers CRTH2, and type 2 cytokines IL-33, IL-5, and IL-4 were significantly increased in PBMCs from patients with gastric cancer compared to healthy controls." (PMID 24741632, 2014). "In this case, the lesions in the fundic gland polyps were positive for CK7, ER, and GATA3 and negative for CK20 and CDX2, supporting metastatic ILC and ruling out primary gastric carcinoma." (PMID 40979040, 2025). "In non-neoplastic mucosa distant from gastric cancer, CVID cases harboured higher Foxp3+, GATA3+ and PD-L1+ intraepithelial lymphocytes (p < 0.001; p = 0.014; p = 0.011)." (PMID 32575504, 2020). "Moreover, it should be emphasised that the high counts of GATA3+ lymphocytes in gastric mucosa may be the consequence of a IL-4 driven T-helper-2-cell differentiation of CD4+ T cells, a mechanism described in the context of H. pylori infection and that could influence gastric cancer pathogenesis." (PMID 32575504, 2020). "In non-CVID patients, there was an increase of Foxp3+, GATA3+, CD4+ and CD8+ T cell counts as well CD20+ B cell counts when the non-neoplastic mucosa distant from tumour was compared to gastric cancer (p = 0.001; p = 0.002; p = 0.006; p = 0.003; p = 0.004, respectively)." (PMID 32575504, 2020).
prostate carcinoma (30 papers, 2009 to 2026). A carcinoma that arises from epithelial cells of the prostate gland. "Accordingly, Pten-deficient mouse model of prostate cancer exhibits a progressive loss of Gata3 expression." (PMID 32894216, 2020). "GATA2 and GATA3 are known AR co-regulators in prostate cancer but any race-specific association is unknown." (PMID 38566104, 2024). "In this model, prostate cancer could be accelerated by an acute loss of Gata3, or significantly delayed by GATA3 maintenance through transgenic expression." (PMID 32894216, 2020). "However, the fact that Gata3 could modulate prostate cancer progression in Pbsn-Cre; Pten-deficient mice known to develop largely from luminal cells raise the possibility of a role in luminal cells." (PMID 32894216, 2020). "Recent studies are exploring GATA3’s expressions in cancer biology, where it is potentially used as a biomarker for diagnosis and prognosis in cancers like breast and prostate cancer." (PMID 39768217, 2024). "An antagonizing role of GATA3 in preventing the progression of prostate cancer has been determined in prior research." (PMID 39768217, 2024). "GATA binding protein 3 (GATA3) is a zinc-binding transcription factor, it is found to bind the promoter of miR-503 and activate miR-503 transcription, however, GATA3 expression was also decreased remarkably in prostate cancer tissues." (PMID 33762949, 2021). "Zinc finger protein 217 (ZNF217) was proven as miR-503 target, it is demonstrated that GATA3/miR-503 axis suppressed the progression of prostate cancer by inhibiting ZNF217 expression." (PMID 33762949, 2021). "For example, GATA3 expression decreases in prostate cancer cells where it acts as a tumor suppressor." (PMID 33013201, 2020). "For example, GATA3 expression is decreased in prostate cancer cells, which promotes cell growth, colony formation, cell migration, and invasion." (PMID 33013201, 2020). "Previous studies have identified that PI3K inhibition can reduce GATA3 protein expression in T cells and prostate carcinomas." (PMID 33298139, 2020). "Firstly, the expressions of GATA3 were significantly decreased in prostate cancer tissues (P<0.01), and the overexpression of GATA3 has been demonstrated to increase the chemosensitivity of DU145 and PC-3 cells to paclitaxel (P<0.01)." (PMID 28599307, 2017). "We then evaluated the role of GATA3 in prostate cancer and if it can be regulated by the treatments of morin and paclitaxel." (PMID 28599307, 2017). "GATA3 regulation happened in the early stage and the outcome of the prostate cancer at the late stage of tumor development that are related to genes MZF1, SREBF1, PRL, and DDIT3." (PMID 20025723, 2009). "The enriched genes included CD4 in cervical cancer, VPS52, NUP62, CRYGD, IL34, GATA3 in prostate cancer and F11, TXNIP, KIT, ASGR2, SERPINF1 in liver cancer, which also provide insight into the molecular mechanisms underlying cancer progression and the potential impact on patient survival." (PMID 37393582, 2023). "In contrast, GATA3 was down-expressed in renal cancers, prostate carcinoma, and others." (PMID 35647011, 2022). "In conclusion, we hereby demonstrate that morin may improve the chemo-sensitivity of prostate cancer cells to paclitaxel through restoring the miR-155-suppressed expression of GATA3." (PMID 28599307, 2017). "In conclusion, morin might be a potential adjuvant of paclitaxel in treating prostate cancer through regulating miR-155/GATA3 axis." (PMID 28599307, 2017). "Therefore it is possible that there is a miR-155/GATA3 axis involved in the antitumor effects of morin as an adjuvant to paclitaxel in treating prostate cancer." (PMID 28599307, 2017). "During human prostate cancer development, GATA3 mRNA levels are found to be significantly reduced in primary prostate tumors, in contrast to GATA2 whose mRNA levels are unchanged in primary prostate tumors and moderately increased in metastatic prostate tumors." (PMID 27374105, 2016).